ACE (angiotensin I converting enzyme)
Diseases named in the same sentence as ACE in open-access papers (continued):
Sharing a sentence is not in itself a finding about the gene and the disease.
gastroesophageal reflux disease (22 papers, 2009 to 2025). A chronic disorder characterized by reflux of the gastric and/or duodenal contents into the distal esophagus. "Heretofore, the CRS has been reported to be affected by the female sex, lacunar infarctions in the basal ganglia, medication with dopaminergic agent, ACE inhibitor, neuroleptics, and gastroesophageal reflux (GER)." (PMID 40943946, 2025). "In patients with a normal chest radiograph, no definitive history of smoking or use of drugs especially angiotensin-converting enzyme (ACE) inhibitors, upper airway syndrome, cough variant asthma, and gastroesophageal reflux disease (GERD) are the most recognized causes of chronic cough." (PMID 32292434, 2020). "Physicians should identify possible triggering factors or comorbidities, such as gastroesophageal reflux disease (GERD), obstructive sleep apnoea (OSA), infections or ACE inhibitor use." (PMID 29471816, 2018).
peripheral arterial disease (22 papers, 2012 to 2025). A disorder of the arteries supplying the upper and lower extremity and the visceral organs. "ACE D/-240 T holotype can predict the occurrence of peripheral arterial disease (PAD) and its complications in the long run and that has been shown by analyzing 281 patients with PAD and 485 control group of the same age and sex and other risk factors." (PMID 33907634, 2021).
rheumatoid arthritis (22 papers, 2012 to 2025). A chronic, systemic autoimmune disorder characterized by inflammation in the synovial membranes and articular surfaces. "Elevated synovial and decreased or normal ACE or ACE2 levels have been found in rheumatoid arthritis (RA)." (PMID 35155468, 2021). "ACE expression is upregulated in the synovial stroma in rheumatoid arthritis, thereby contributing to synovial hypoxia and proliferation; rheumatoid arthritis patients have higher ACE concentrations when compared with healthy controls." (PMID 27657933, 2016). "As observed in patients with rheumatoid arthritis, patients with OA have higher levels of ACE activity in synovial fluid than controls." (PMID 27657933, 2016). "These lesions can also appear as a response to ACE (angiotensin-converting enzyme) inhibitors and beta-blockers (antihypertensive drugs), NSAIDs (nonsteroidal anti-inflammatory drugs), and antimalarial medications used in rheumatoid arthritis." (PMID 34576672, 2021). "Interestingly, ACh showed that is not correlated with ACE V̇O2peak, which does not confirm to previous findings that have shown association of endothelial-dependent function with the improvement in aerobic capacity in patients with rheumatoid arthritis." (PMID 29871697, 2018).
systolic heart failure (22 papers, 2010 to 2025). Heart failure caused by abnormal myocardial contraction during systole leading to defective cardiac emptying. "Circulating ACE concentration is controlled by a genetic polymorphism of the ACE gene (an insertion/deletion polymorphism, I/D polymorphism), being implicated in systolic heart failure." (PMID 34359878, 2021). "Of the top 5 PPOs, three PPOs increased (ACE inhibitor & combinations; statin therapy & combinations; beta-blocker & stable systolic heart failure) and two PPOs (laxatives & opioids; proton pump inhibitor & combinations) did not change over the years." (PMID 33269418, 2021). "Current guidelines should be implemented in standard medical therapy for systolic heart failure, including ACE inhibitors, beta-blockers, mineralocorticoid receptor antagonists, and ARNI (angiotensin receptor-neprilysin inhibitor)." (PMID 31134062, 2019). "Patients with familial DCM are treated with angiotensin-converting enzyme (ACE) inhibitors, β-blockers and diuretics similar to those used for other systolic heart failure conditions." (PMID 28883014, 2017). "The standard treatment of systolic heart failure is currently angiotensin-converting enzyme (ACE) inhibitors, angiotensin II receptor blockers (ARBs), beta blockers, and aldosterone antagonists." (PMID 22811735, 2012). "In parallel to the general recommendations in all patients with systolic heart failure, beta-blockers and/or ACE inhibitors/ARBs seem to be highly beneficial and should always be considered early in the treatment of PPCM with uptitration to the maximum tolerated dose." (PMID 23812247, 2013).
Parkinson disease (21 papers, 2008 to 2025). A progressive degenerative disorder of the central nervous system characterized by loss of dopamine producing neurons in the substantia nigra and the presence of Lewy bodies in the substantia nigra and locus coeruleus. "We further investigated whether any effect of ACE expression on AD risk is mediated through changes in blood pressure and whether effects extend to Parkinson disease, small-vessel disease, or cognitive function in a Mendelian randomization paradigm." (PMID 36046424, 2022). "In Parkinson's and Alzheimer's patients, ACE activity is higher and is considered to reflect a response to inflammation of the brain." (PMID 37153428, 2023). "Most recently, ACE-Is as renin–angiotensin system inhibitors were identified to be directly neuroprotective in a zebrafish model for Parkinson's disease." (PMID 35098999, 2022). "Barberry, by controlling the ACE enzyme (angiotensin converting enzyme) in the brain or by antioxidant property, can reduce the symptoms of Parkinson's disease." (PMID 31827685, 2019). "Peganum harmala L. extract, which has angiotensin converting enzyme (ACE) inhibitory effect, is considered to evaluate oxidative stress inhibition and Parkinson's disease improvement." (PMID 27610168, 2016). "The idea of altering the activity of RAS for therapeutic benefit in Parkinson’s was first tested in Melbourne by demonstrating in a prospective study that the angiotensin converting enzyme (ACE) inhibitor, perindopril, reduces levodopa-induced dyskinesias." (PMID 25645462, 2015). "Parkinson's disease patients treated with the ACE inhibitor perindopril revealed improved motor responses to the DA precursor 3,4-dihydroxy-L-phenylalanine." (PMID 23213621, 2012). "Some components of RAS have been found to be altered in Parkinson’s disease (PD) patients: ACE activity was increased in the cerebrospinal fluid and AT1R expression was decreased in the brain in a post-mortem study, which was associated with the loss of dopaminergic neurons." (PMID 34302265, 2021).
ischemia (20 papers, 2008 to 2025). A hypoperfusion of the BLOOD through an organ or tissue caused by a PATHOLOGIC CONSTRICTION or obstruction of its BLOOD VESSELS, or an absence of BLOOD CIRCULATION. "When the downregulation of ACE leads to insufficient production of Ang II, the regulatory function of retinal blood vessels is impaired, which may cause local ischemia and hypoxia in the retina." (PMID 40282274, 2025). "Drugs that enhance nitric oxide (NO) release (e.g., statins, calcium antagonists, ACE-inhibitors, dexamethasone), NO, or NO donors had to be administered prior to ischemia to protect the myocardium against IR injury, making their clinical use problematic." (PMID 41510231, 2025). "Situations where B1R synthesis is induced include ischemia, chronic hyperglycemia, and also, interestingly, ACE inhibitor therapy." (PMID 31316987, 2019). "Administration of nitric oxide, NO donors, or drugs that enhance NO release (statins, calcium antagonists, ACE inhibitors, and dexamethasone) prior to ischemia protects the myocardium against MIRI." (PMID 27042175, 2016). "Weber reported local production of angiotensin II within the myocardium, suggesting a role for intrinsic myocardial activation of ACE secondary to ischemia." (PMID 18353184, 2008). "By comparing different ACE inhibitors, captopril significantly reversed increases in lactate dehydrogenase (LDH) release as a marker of cardiac damage induced by ischemia with a marked degree and duration of ACE inhibition ex vivo attributable to differences in distribution to key organs." (PMID 40806350, 2025). "However, the deleterious cardiac effects of ACE gene duplication can be partially prevented by renin inhibition, indicating that both kinin depletion and enhanced local angiotensin II formation are involved in ACE-mediated cardiac damage in ischemia." (PMID 31316987, 2019). "Thus, zofenopril exerts cardioprotective effects beyond ACE inhibition by augmenting H2S and NO before ischemia and limiting the myocardial damage after I/R." (PMID 27381758, 2016). "On the other hand, the angiotensin converting enzyme (ACE)—producer of Ang II—deactivates bradykinin production; bradykinin is a peptide that may induce tissue protection during ischemia by promoting the release of prostaglandins which, in turn, improve blood flow and oxygen delivery to the heart." (PMID 29135932, 2017). "Clinical pretreatment with drugs, such as statins, certain calcium antagonists, angiotensin-converting enzyme (ACE) inhibitors, or dexamethasone, has been additionally reported to increase the release of NO and protect the myocardium against ischemia reperfusion injury." (PMID 30510628, 2018).
lupus (19 papers, 2009 to 2025). "cSiO2 also elicited extracellular granzyme B, which has been linked to lupus pathogenesis by cleaving autoantigens and exposing neoepitopes, as well as ACE and the aspartic acid protease renin 1, two key enzymes in the renin-angiotensin system." (PMID 35126352, 2021). "The rational for studying the effect of ACE inhibitors on humoral response relies on the fact that enalapril and captopril are included in the list of medicines implicated in drug-induced lupus." (PMID 27409332, 2016). "ACE polymorphisms have also been associated with severe systemic lupus erythematosus (SLE) and ACE inhibitors slow SLE progression." (PMID 36016727, 2022). "ACE inhibitors, such as captopril and perindopril, improve cognitive status and neuronal functions in lupus-prone mice." (PMID 36078885, 2022). "Angiotensin-converting enzyme (ACE) gene is indispensable for endothelial control and vascular tone regulatory systems, usually affected in Systemic Lupus Erythematosus (SLE)." (PMID 30618805, 2018). "Genes, like angiotensin-converting enzyme (ACE) or angiotensinogen (AGT), that specifically increase kidney susceptibility to lupus pathogenesis have also been described." (PMID 22761632, 2012). "Additionally, ACE inhibitors treatment in a lupus-prone model suppressed microglial activation, which in turn preserved dendritic complexity in hippocampal neurons." (PMID 36078885, 2022). "To further test other important candidates of the KKS system, we focused on ACE, because captopril, an ACE inhibitor is a widely prescribed drug for lupus patients with kidney disease and we anticipated captopril to have other immunoregulatory effects other than regulating blood pressure." (PMID 29456540, 2018). "In autoimmunity, ACE may be a candidate marker or gene to determine if patients will have severe cases of SLE and RA, whilst its inhibition has shown promise in maintaining inflammation and associated injury in lupus patients." (PMID 36016727, 2022). "We have shown recently that bradykinins (BK) and captopril [an ACE inhibitor (ACEi)] suppressed Type I IFN responses in murine dendritic cells (DCs) from normal and lupus-prone mice and in human peripheral blood mononuclear cells (PBMC)." (PMID 33042154, 2020). "Accordingly, we have demonstrated that captopril, an ACE inhibitor with a thiol group, inhibits the production of IL-10 and IL-4 without affecting IL-5, IFN-γ, and IL-2 synthesis in lupus mice." (PMID 27409332, 2016).
fibrosis (18 papers, 2016 to 2025). the formation of excess fibrous connective tissue in an organ or tissue in a reparative or reactive process. "Some angiotensin-converting enzyme (ACE) inhibitors have proven to protect the lungs from fibrosis after IR exposure." (PMID 32545674, 2020). "Besides its direct glomerular effect, ACE inhibition is known to have a major influence on repair and regeneration of peritubular fibrosis secondary to glomerular injury." (PMID 34900856, 2021). "In line with this, we found an increased ACE, MMP2, and MMP7 mRNA expression, but also reduced APEH, ECE1, MBP, and NEP in samples with an advanced fibrosis grade." (PMID 39201455, 2024). "Nevertheless, QFHXD and prednisone decreased ACE, AGT, and AT1R protein expressions (vs fibrosis group, P<0.01)." (PMID 36594067, 2023). "Classical clinical drugs, such as β receptor blocker, angiotensin-converting enzyme (ACE) inhibitors, and aldosterone receptor antagonists, were demonstrated to reverse cardiac fibrosis and ameliorate remodeling in post-MI patients." (PMID 35474903, 2022). "Furthermore, the current results are in agreement with observations of a previously published study showing that accumulation of endogenous Ac-SDKP in ACE N-terminal catalytic site-KO mice alleviates BLEO-induced lung injury, in particular fibrosis." (PMID 27029074, 2016).
hyperuricemia (18 papers, 2017 to 2026). An abnormally high level of uric acid. "Among the patients with hyperuricemia in this study, 20 were taking diuretics, 20 were taking ACE inhibitors or ARBs, and 20 were taking beta blockers." (PMID 35742447, 2022). "Increased proteinuria and hyperuricemia were significantly associated with a faster decline in RKF, while angiotensin converting enzyme (ACE) inhibitors and angiotensin II receptor blockers (ARBs) slowed the decline of RKF." (PMID 34237104, 2021). "Hyperuricemia can directly or indirectly activate the RAS system’s ACE/AII/AT1 axis, stimulating oxidative stress and cytokine release, promoting inflammatory responses, and also participating in cardiac electrical remodeling, inducing morphological changes in atrial cardiomyocytes." (PMID 40469443, 2025). "In the present study, 63.6% of the patients were taking ACE inhibitors or ARBs at baseline, which could have attenuated the potential effects of hyperuricemia on the activity of the renin-angiotensin system." (PMID 33765101, 2021). "The relatively high percentage of patients with hyperuricemia in this study who were treated with ACE inhibitors or ARBs may reflect an abnormally high prevalence of cardiovascular and renal disease in this population." (PMID 33059648, 2020).
hypotension (18 papers, 2011 to 2025). "Hypotension was observed in five (25%) patients, including one patient prescribed an angiotensin-converting enzyme (ACE) inhibitor." (PMID 38047156, 2024). "Although the mechanisms underpinning ACE inhibitor-related dizziness remain uncertain, dizziness is likely a symptom of orthostatic hypotension." (PMID 35886227, 2022). "Although orthostatic hypotension has been described as a side effect of ACE inhibitors, it usually occurs only as a first-dose phenomenon or during treatment in conjunction of dehydration or other hypotensive drugs." (PMID 36048833, 2022). "Renin released in response to increased Na+ retention and local renal hypotension converts angiotensinogen to angiotensin I (Ang I), which is further cleaved to give Ang II by the angiotensin converting enzyme (ACE)." (PMID 30314359, 2018). "Because of its vasodilating properties, Crataegus may enhance the effect of vasodilating medicines, such as ACE inhibitors, calcium channel blockers and nitrates, eliciting orthostatic hypotension." (PMID 39598401, 2024). "In a biventricular circulation the use of ACE inhibitors may lead to orthostatic hypotension and in Fontan patients, with their critical fluid balance, these circulatory effects may be even more deleterious." (PMID 36048833, 2022). "The main findings were that both the exercise intensity and the presence of I allele of ACE gene may interfere on NO2- liberation and post-exercise hypotension (PEH) occurrence in hypertensive elderly women." (PMID 22136292, 2011). "Therapy with high dose steroids, loop diuretics, and ACE-inhibitors did not affect his proteinuria and he was seriously disabled because of symptomatic orthostatic hypotension and anasarca." (PMID 30886753, 2019).
lymphoma (18 papers, 1980 to 2026). A malignant (clonal) proliferation of B- lymphocytes or T- lymphocytes which involves the lymph nodes, bone marrow and/or extranodal sites. "Our control group included all patients with documented ACE levels, including those with conditions that elevate ACE levels, such as lymphomas, cirrhosis, and interstitial lung disease." (PMID 39768579, 2024). "Studies are underway which will evaluate the time-dependent changes in cardiac function and examine the effect of an ACE-inhibitor on myocardial performance, mainly in children with different types of leukaemia and lymphomas." (PMID 19623176, 2009). "Overall, it should be noted that serum ACE, lysozyme and sIl-2R may also be elevated due to other diseases, such as malignant lymphoma or infections." (PMID 35011651, 2021). "For instance, macrophages modified to overexpress the gene for angiotensin-converting enzyme (ACE) conveyed resistance to lymphoma and melanoma in mouse model; the protective effect was accompanied by increased production of IL-12 and nitric oxide and decreased production of IL-10." (PMID 32599709, 2020). "Serum angiotensin-converting enzyme (ACE) and soluble interleukin-2 receptor (sIL-2R) levels were markedly elevated, strongly suggesting malignant lymphoma." (PMID 42005268, 2026).
myocardial ischemia (18 papers, 2004 to 2025). A disorder of cardiac function caused by insufficient blood flow to the muscle tissue of the heart. "Loss of the cardioprotective effect of ACE inhibitors in cardiac ischemia in K1 and kinin deficient mice is explained by the well-documented role of kinins in the beneficial effect of the drugs in this experimental model." (PMID 31316987, 2019). "Several lines of evidence indicate that the actions of ACE inhibitors in cardiac ischemia are due to their effect on the inhibition of endogenous BK degradation rather than their effect on Ang II inhibition." (PMID 37892221, 2023). "We therefore investigated how lowering of AngII levels due to ACE inhibition impacts emergency myelopoiesis in cardiac ischemia." (PMID 33807982, 2021). "On the other hand, two of the upstream targets, epidermal growth factor receptor (EGFR) and ACE, have also been proposed as potential targets for myocardial ischemia." (PMID 23028693, 2012). "It was earlier reported that inhibitors of ACE, which is identical to kininase II, protect against cardiac ischemia in in vivo and ex vivo models by limiting infarct size and protect against reinfarction." (PMID 27713243, 2010). "The positive effects of ACE inhibition and AT1R blockade during myocardial ischemia could also be caused by the increased production of NO and Bk." (PMID 38279313, 2024). "Indeed, it is known that angiotensin II contributes to heart damage during ischemia/ reperfusion and that Ang II AT1 receptor blockers as well as ACE inhibitors have protective effects in experimental animal models of myocardial ischemia as well as in humans." (PMID 20066151, 2009). "If this is the case, the beneficial effect of ACE inhibitors and angiotensin II AT1 receptor blockers during myocardial ischemia is related, at least in part, to the suppression of the effect of angiotensin II on cell volume." (PMID 20066151, 2009). "Indeed, the inhibition of ACE and blockade of AT1R increased cardiac bradykinin and NO levels, and elevated coronary blood flow in another study on dogs with myocardial ischemia induced by the reduction of coronary perfusion pressure." (PMID 38279313, 2024). "Furthermore, women were less likely than men to undergo coronary artery angiography or noninvasive tests for myocardial ischemia, as well as percutaneous coronary intervention (PCI) or coronary artery bypass grafting (CABG), or to receive ACE inhibitors or lipid-lowering drugs." (PMID 32099582, 2019).